TGFB1 (transforming growth factor beta 1)
Diseases named in the same sentence as TGFB1 in open-access papers (continued):
Sharing a sentence is not in itself a finding about the gene and the disease.
tumor (continued). "Additionally, The role of TGFβ-1 in cancer progression has been shown to be multifaceted, depending on the tumor stage." (PMID 31350967, 2019). "Interestingly, our results reveal a down-regulation of TGFβ1 and an up-regulation of TGFβ2, TGFβ3, Smad4 and RAC1b in treated cells, suggesting that PRP treatment promotes the TGFβ pathway role via a tumour suppressive route." (PMID 31388092, 2019). "Ligand VEGFC (a positive regulation signaling of lymph angiogenesis) could interact with receptor FLT4 to upregulate target gene TGFB1, which is a tumor promoter in this carcinogenic progression to induce cancer cell proliferation, migration and EMT." (PMID 31126066, 2019). "Interestingly, in non-tumour-bearing mice, Bmp7 expression is substantially higher in the brain than the lungs, whereas the expression of Tgfb1 is higher in the lungs compared with the brain." (PMID 30642388, 2019). "Similar to other members of the TGFβ superfamily, such as TGFβ1, Activin A has been shown to play dual roles in cancer progression depending on the genetic and cellular context as well as tumor stage, exerting early tumor suppressive and late pro-metastatic effects." (PMID 30805303, 2019). "Thus, similar to primary tumor growth, metastatic outgrowth is supported by the surrounding stroma including TGFβ1 and periostin, pro-inflammatory cells, local fibroblasts, and supportive ECM components." (PMID 31921628, 2019). "Since α-SMA and TGFβ1 are specific markers for myofibroblasts, we analyzed the levels of these two proteins, as well as a fibrotic marker Collagen I and fibronectin at the site of skin injury." (PMID 30728320, 2019). "In addition, TGFβ1 has been found to exert a tumor promoter function, which coincides with the progression of the tumor and the presence of EMT and metastasis." (PMID 31905709, 2019). "This may be related to the involvement of TGFB1 in Adipose stromal cells-(ASCs-) mediated tumor fibrosis, extracellular matrix remodeling, and epithelial-mesenchymal transition (EMT)." (PMID 31485443, 2019). "Meanwhile, the tumor sphere formation assays also demonstrated that TGIF1 loss significantly increased the tumor sphere-forming ability of PDAC cells with or without TGFβ1 treatment." (PMID 31109321, 2019). "However, the combination of anti-PD-1 with blockade of TGFβ1 activation leads to tumor growth delay, a substantial number of complete responses, and prolonged survival coupled with increased effector CD8+ T cell infiltration." (PMID 30400822, 2018). "Interestingly, HSC activation resulted in up-regulation of Tgfb1 expression, which in turn maintained pro-tumor gene expression in TANs and TAMs and thereby promoted carcinogenesis." (PMID 29855567, 2018). "Finally, given the suppressive role of CLDN7 during the process of EMT induced by TGFB1 and Musashi-2, it is a novel strategy to inhibit tumor progression by increasing CLDN7 expression." (PMID 30428910, 2018). "The enrichment of Tregs in tumours could be induced by the conversion of FOXP3- T cells into FOXP3+ T cells in the presence of TGFβ1 and retinoic acid." (PMID 30417146, 2018). "Particularly in GBM, TGFB1 is one of the most powerful cytokines secreted by the tumor itself." (PMID 30366472, 2018). "Treatment of EMT6 tumor-bearing mice with M7824 and M7824mut significantly reduced plasma levels of TGFβ1 after treatment, indicating their ability to bind to murine TGFβ1 in vivo." (PMID 29721396, 2018).
tumor (continued). "Compared to the macrophages in WT group samples, the macrophages isolated from PKN2-WT tumor showed significantly higher expression of Il1b, Tnf, Cxcl9, Il23, Ros1 and Il12b and significantly lower expression of Tgfb1, Vegfa, Egf, Retnla and Il10, illustrating predominant M1 phenotype." (PMID 29368606, 2018). "The tumor suppressive effects of TGFβ1 are lost in cells that have undergone EMT." (PMID 30119678, 2018). "Moreover, when in direct cell-cell contact with GBM cells, MSC elicited an increased proliferative and invasive tumor cell behavior under 3D conditions, as well as accelerated tumor development in nude mice, independently of paracrine TGFB1." (PMID 29872504, 2018). "Keratinocytes cultured from TGFβ1-null mice have marked genomic instability that could accelerate tumor progression." (PMID 29234487, 2017). "Activated platelets can supply sufficient TGFβ1 to enable successful metastasis of tumour cells." (PMID 28737696, 2017). "Moreover, a recent report demonstrated that the tumor-enhancing activities of TNFα-primed adipose tissue-derived MSCs are mediated by TGFβ1, suggesting close interactive relationships between these two seemingly opposing cytokines." (PMID 28553282, 2017). "Moreover, TG2 inhibition by 1-155 results in reduced expression of TGFβ1 in whole cell lysates and in matrix bound TGFβ1 in primary tumour CRCs RKO and SW480." (PMID 28223538, 2017). "Furthermore, 32% of patients with low tumor TGFβ1 expression have high MKI67 expression, whereas only 7% of patients in the high TGFβ1 expression group have high MKI67 expression (P = 0.009)." (PMID 27895310, 2017). "The Multiple Beam Search (MBS) algorithm learned interactions from data and discovered that hsa-miR-21, hsa-miR-10b, hsa-miR-448, and hsa-miR-96 interact with oncogenes, such as, CCND2, ESR1, MET, NOTCH1, TGFBR2 and TGFB1 that promote tumor metastasis, invasion, and cell proliferation." (PMID 28793339, 2017). "To further investigate the impact of factors released by TNFα + TGFβ1-stimulated MSCs on tumor cell motility, we determined the scattering of MCF-7 cells from spheroid tumor masses, demonstrated by our published study to correlate with a more aggressive behavior of the cells." (PMID 28553282, 2017). "Our results strongly suggest that the tumor phenotype could be in part dependent on pVHL172-mediated upregulation of TGFB1 and of some metalloproteases." (PMID 29100286, 2017). "Instead, given their higher expression of Il-10 and Tgfβ1, a more rational approach might be to add immune modulators to bolster our current combination therapy by further reducing tumor immunosuppression." (PMID 28539588, 2017). "On the basis of our data, we propose a model whereby LOX activates the secreted protease HTRA1, which inhibits TGFβ1 signalling, causing increased expression of the EGF-like domain containing protein MATN2, which then enhances EGFR signalling to drive tumour growth and metastasis." (PMID 28416796, 2017). "Additionally, numerous transcriptional regulators act downstream of NRP-1 such as SNAI117, a transcriptional repressor pivotal for cell differentiation and survival that reverses the tumor suppressive effects induced by TGFβ1 in early stage breast cancer." (PMID 28607365, 2017). "Transforming growth factor beta 1 is both expressed by tumor cells and adjacent stroma." (PMID 28049456, 2017). "Thus, our findings demonstrate a TNFα + TGFβ1-driven pro-inflammatory fate in MSCs, identify specific molecular mechanisms involved, and propose that TNFα + TGFβ1-stimulated MSCs influence the tumor niche." (PMID 28553282, 2017). "Similarly, glioblastoma CTCs isolated from patients as well as from a PDX mouse model, when compared with their matched parental tumor, show the upregulation of RNA encoding for the mesenchymal genes SERPINE1, TGFB1, TGFBR2, and vimentin." (PMID 28544498, 2017).
tumor (continued). "Through proof of concept tests, we could demonstrate that TGFβ1, a cytokine that is important for tumor–stroma interactions and transdifferentiation of fibroblasts to carcinoma-associated fibroblasts (CAFs), induced autophagy in fibroblasts." (PMID 28515430, 2017). "Hence, tumour microenvironment with high TGFβ1 content shall favour NPC escape from the “killing effect” of exogenous radiation treatment." (PMID 28423621, 2017). "In BC patient samples, the tumor invasiveness is driven by the TGFβ1 signaling pathway that promotes the EMT through cancer-associated fibroblasts (a major component of the cancer stroma); in this system, TGFβ1 is overexpressed in the presence of an upregulated ZEB2-AS1 (together with ZEB2)." (PMID 29165379, 2017). "As such, CMS1/CMS4 cancer cells may induce pro-metastatic behavior of CAFs through TGFβ1/2 paracrine signaling, illustrating how cancer cell-intrinsic expression may modulate the tumor microenvironment." (PMID 28683746, 2017). "As microglia treated by IFNγ and TNFα supposedly represent a population of M1 activated microglia and TGFβ1 treated cells a subpopulation of M2 activated microglia, the tumor cells in our experimental system seem to shift microglia towards a more M2-like phenotype." (PMID 28008153, 2017). "Evidence from animal models points to tumor-derived transforming growth factor beta 1 (TGF-β1) as a key mediator in converting fibroblasts in the tumor stroma to alpha-smooth muscle actin (αSMA)-expressing myofibroblasts termed cancer-associated myofibroblasts or CAFs2." (PMID 28878242, 2017). "Our findings propose that when the TME is enriched with both cytokines, as may often be the case in malignancy, TNFα + TGFβ1 would act not only on the tumor cells but also may induce the release of pro-inflammatory and tumor-promoting factors by MSCs." (PMID 28553282, 2017). "FOXP3 expression was most potently induced by tumours secreting higher levels of total and active TGFβ1 and this induction could be potently counteracted with IL-21, restoring T cell proliferation." (PMID 28239749, 2017). "Through proof of concept experiments using TGFβ1 as a model factor, we could demonstrate real time monitoring of autophagy induction in fibroblasts by single tumor cells." (PMID 28515430, 2017). "TGFβ1 acts as an inhibitor of proliferation during the initial stages of tumor development." (PMID 27144026, 2016). "Moreover, the authors discovered that TGFβ1 was required and sufficient to promote the transition of the high-density neutrophils into the tumour-supportive low-density neutrophils." (PMID 27515461, 2016). "This raises the possibility that GSK2126458 could interfere with the fibrogenic effects of TGFβ1 signalling at clinically attainable doses, while potentially sparing its essential homeostatic and tumour suppressor functions." (PMID 27103349, 2016). "These unrelated observations might have indicated that the αvβ6-dependent activation of TGFβ1 in part regulated tumour immune surveillance, as shown subsequently for αvβ8." (PMID 27515461, 2016). "Due to the assessed transcriptome changes and upregulation of TGFB1 and TGFB2 itself, it is suggested that knockdown of ERβ resulted in activation of TGFβ1/2 signaling, which resulted in induction of genes with known functions in extracellular matrix and tumor cell invasion." (PMID 28003019, 2016). "To discover whether endogenous autocrine TGFβ expression is required for tumour formation, we generated ligand knockdown clones of A375(M2) cells using stably transfected shRNA constructs targeting TGFβ1." (PMID 27835901, 2016). "A high expression of TGFβ1 was associated with poor survival compared with lower TGFβ1 expressing tumours; 5-year survival among patients with a lower TGFβ1 expression was 70%, whereas >50% of the patients with higher TGFβ1 expression succumbed to their disease in this period." (PMID 26987776, 2016).
tumor (continued). "Therefore, integrins that are able to activate TGFβ1 in vivo are probably also likely to modulate tumour progression indirectly via the local production of active TGFβ1." (PMID 27515461, 2016). "Likewise, TGFβ1 expression levels by tumor cells in patients with advanced gastric adenocarcinoma are inversely correlated with the cytolytic activity of NK cells isolated from the ascites and peripheral blood of these patients." (PMID 27589814, 2016). "Similarly, the TGFβ1 receptor inhibitor, SB431542, inhibited TGFβ1 stimulation of tumor cell motility to an extent comparable to SSA." (PMID 26769851, 2016). "Any of these alterations to TGFβ1 signaling pathway components can shield tumor cells from the growth inhibitory effects of TGFβ1 while still allowing the tumor-promoting activities of this cytokine to be triggered in other cells within the milieu of the tumor microenvironment." (PMID 27589814, 2016). "Thus, depletion of N2 neutrophils within TGFβ1-rich mouse tumours significantly reduces tumour size, supporting the concept that separate populations of anti-tumour and pro-tumour neutrophils are regulated by active TGFβ." (PMID 27515461, 2016). "Because TGFβ1 is known to compromise CTL effector function, several trials have been designed to investigate whether introducing TGFβ1 resistance into adoptively-transferred CTL can boost the anti-tumor efficacy of these cells." (PMID 27589814, 2016). "TGFβ1 is one of the most abundant cytokines in the tumor microenvironment." (PMID 27851822, 2016). "However, clearly, tumour cells often secrete latent TGFβ1 and can promote the generation of myofibroblasts and, thus, we can reasonably assume that they derive benefit from activating fibroblasts to myofibroblasts." (PMID 27515461, 2016). "Finally, ERRα and TGFb1 expression levels were significantly positively correlated in primary CRPC tumor samples (n = 140, r = 0.684, P = < 0.0001)." (PMID 27776343, 2016). "In particular, macrophages exposed to TGFβ1 have been shown to acquire an M2-like phenotype characterized by a number of tumor-promoting functions, including the ability to promote angiogenic activity, suppress T cell proliferation and induce CD4+ FOXP3+ Treg differentiation." (PMID 27589814, 2016). "In this section, we summarise both empirical data, whereby researchers have directly examined the role of integrin-dependent TGFβ activity in tumour progression and inferred data, whereby we can reasonably assume that integrin-dependent TGFβ1 activation is at play." (PMID 27515461, 2016). "Recent reviews have described the role of TGFβ1 in the regulation of the tumour microenvironment." (PMID 27515461, 2016). "This has implications for the TGFβ1-dependent modulation of the tumour microenvironment in cancer." (PMID 27515461, 2016). "In the context of the tumor microenvironment, therefore, various sources of TGFβ1 may contribute to T cell dysfunction and ultimately limit the efficacy of anti-tumor immune responses mediated by these cells." (PMID 27589814, 2016). "Indeed, FACSorted CAFs from Wnt7a high 410.4/4T1 tumours consistently show higher levels of Tgfb1 expression as compared with Wnt7a low 4T07 tumours." (PMID 26777421, 2016). "Thus, numerous examples link the αvβ6-dependent activation of TGFβ1 as a promoter of pre-clinical tumour progression." (PMID 27515461, 2016). "Compared with the hMSC without TGFβ-1 gene transfection, the highest tumor inhibition rate of MHCC97-H animal models was observed in the fourth week after TGFβ-1 infected hMSC engraftment, and the tumor inhibition rate gradually reduced with the prolongation of time." (PMID 26003220, 2015). "hMSC and TGFβ-1 gene infected hMSC exhibit anti-tumor activity in a time-dependent manner." (PMID 26003220, 2015). "TGFβ-1 plays dual roles in inhibiting and promoting tumor growth." (PMID 26003220, 2015).
tumor (continued). "Interestingly, in a series of resected adenocarcinomas of the distal esophagus, TGFB1 mRNA was expressed at significantly higher levels in tumor tissues compared to squamous epithelium and Barrett's mucosa." (PMID 26447543, 2015). "But it was reported that the exogenous TGFβ-1 cytokine could promote tumor migration and metastasis." (PMID 26003220, 2015). "Such discrepancies might be explained by the different effect of TGFβ1 expression in early versus advanced tumor stages, the heterogeneous population included in such retrospective trials and the crosstalk between TGFβ signaling and other pathways." (PMID 26040677, 2015). "Accordingly, over-expressing of miR-573 in tumor cells inhibited TGFβ1-induced EMT." (PMID 26451614, 2015). "In addition to TGFβ1, large tumor size (HR = 2.10, 95 % CI: 1.25 to 3.49, p = 0.005) and high SBR grade (HR = 1.97, 95 % CI: 1.16 to 3.36, p = 0.013) were the only factors that independently predicted shorter DMFS in the multivariate model." (PMID 26040677, 2015). "The expression of both MRC2 and transforming growth factor (TGFβ1) was detected in tumor tissues and adjacent liver tissues from 96 HCCs by immunohistochemistry staining, and it was found that MRC2 expression in HCC tissues was significantly higher than in adjacent liver tissues." (PMID 25162823, 2014). "It appears, that many epithelial tumors escape growth inhibition by TGFβ1, and TGFβ1 secretion by cancer may contribute to late tumor progression." (PMID 24684802, 2014). "In order to test the hypothesis that disruption of galectin-3 in either macrophages or tumor cells could affect VEGF secretion in response to TGFβ1 levels, we tested in vitro whether BMDM and/or cell lines secrete VEGF when cultured in TGFβ1-enriched medium." (PMID 24421272, 2014). "Instead of acting as a cell cycle regulator in normal cells to induce apoptosis or cease cell proliferation, TGFβ1 from tumor exosomes assists in immune response evasion by tumor cells and also induces an antiproliferative effect on tumor growth and lymphocytes." (PMID 24460816, 2014). "Collectively, TGFβ1 is considered to be a tumor promoter in PCa tissues." (PMID 25202359, 2014). "TGFβ1 reduces tumor suppressor, E-cadherin, expression in various epithelial-derived cancers." (PMID 24684802, 2014). "TGFβ1-mediated down-regulation of E-cadherin contributes to tumor invasion and proliferation." (PMID 24684802, 2014). "Therefore, it is important to explore the key factors which play an important roles in the conversion of TGFβ1 function from a tumor suppressor to a tumor promoter." (PMID 25162823, 2014). "Thus, TGFβ1 secreted in tumor stroma of DCIS is described as a critical permissive factor to initiate proinvasive pathways through ECM decorin deficiency in CAF." (PMID 25526025, 2014). "With pbMOO approach, the functional unknown protein OCIAD2 was also enrolled into a signal pathway “TGFβ1- TGFβR1- SMAD2/3- SMAD4- AR-OCIAD2” in tumor and adjacent microenvironment." (PMID 24949437, 2014). "In addition to its effects on tumor cells, TGFβ1 is also involved in the response of normal tissues to radiation or radiochemotherapy." (PMID 23840350, 2013). "Thus, our results suggest that suppression of NIH3T3 cell migration by km23-1-siRNA-RKO CM was likely due to a blockade of the paracrine effects of tumor cell-secreted TGFβ1." (PMID 23755307, 2013). "Overexpression of TGFβ1 in primary CRC is a poor prognostic predictor and correlated with advanced stage of disease, increased risk of recurrence, shorter post-operative survival, particularly in early tumours and decreased overall survival." (PMID 24180698, 2013). "TGFβ1 in paracancerous liver tissue was positively correlated with the tumor size." (PMID 23251252, 2013).